ERAP2 (endoplasmic reticulum aminopeptidase 2)
Diseases named in the same sentence as ERAP2 in open-access papers (continued):
Sharing a sentence is not in itself a finding about the gene and the disease.
pancreatic cancer (continued). "Besides, gemcitabine significantly increased the mRNA and protein levels of ERAP2 in pancreatic cancer cells." (PMID 36214762, 2022). "More importantly, we screened gemcitabine treated patients in the TCA-PAAD pancreatic cancer data set and measured their treatment efficacy, and found significantly lower ERAP2 expression values in the effective group (PR/CR) than in the ineffective group (PD)." (PMID 36214762, 2022). "We then examined the ERAP2 levels in pancreatic cancer cell lines with gemcitabine treatment." (PMID 36214762, 2022). "As a downstream molecule of mTOR, ERAP2 inhibition may have better potential for pancreatic cancer treatment and blockade of gemcitabine resistance." (PMID 36214762, 2022). "Interestingly, ERAP2 knockdown also significantly increased sensitivity to gemcitabine in these two pancreatic cancer cell lines." (PMID 36214762, 2022). "Finally, we adopted the immunohistochemical data of pancreatic tissues and pancreatic tumors in ProteinAtlas database to verify the expression of the protein level of ERAP2, and further confirmed the high expression of ERAP2 in pancreatic tumor." (PMID 36214762, 2022). "Similarly, we found that ERAP2 also closely relevant to the survival of pancreatic cancer patients." (PMID 36214762, 2022). "First, we analyzed the relationship between ERAP2 expression and gemcitabine IC50 in pancreatic cancer cells in the GDSC1 and GDSC2 datasets." (PMID 36214762, 2022). "Next, we analyzed the ERAP2 expression in pancreatic cancer by the GEPIA database and found that ERAP2 was significantly overexpressed in pancreatic cancer samples, which further demonstrated the cancer-promoting effect of ERAP2." (PMID 36214762, 2022). "Overall, these findings demonstrate that ER stress and the resulting UPR signaling pathway trigger ERAP2-dependent autophagy and PSC activation, uncovering the benefits of targeting ERAP2 as a potentially promising strategy for the treatment of pancreatic cancer." (PMID 40226591, 2025). "We adopted R package to plot the Forest plot of this model, and found that the P values of ERAP2 and DOCK11 were both less than 0.05, suggesting that they could be independent prognostic factors for pancreatic cancer patients treated with gemcitabine, respectively." (PMID 36214762, 2022). "Compared to the noncancerous cells S-G and 293T, the ERAP2 can be detected in 4 OSCC cell lines, pancreatic cancer cell PANC1, ovarian cancer cell SKOV3, and kidney cancer cell 786-O." (PMID 28977897, 2017).
HIV-1 infection (6 papers, 2017 to 2024). The type species of lentivirus and the etiologic agent of acquired immunodeficiency syndrome (AIDS). "We sought to investigate the potential role of ERAP2 in altering HIV-1 infection outcome and if there was evidence of additive or synergistic interaction between ERAP and HLA." (PMID 38980912, 2024). "In this study of an Australian population, where the effects of known HLA and CCR5 determinants are evident, we show that genetic variation in ERAP2 additionally influences HIV-1-infection outcome." (PMID 38980912, 2024). "We further sought to examine the interaction effect of ERAP2 haplotypes and viral adaptations on HIV-1 infection outcome." (PMID 38980912, 2024). "The mechanism by which exogenous ERAP2 interferes with HIV-1 infection/replication is under investigation." (PMID 31379846, 2019). "rhERAP2 could also further down-regulate susceptibility to HIV-1 infection/replication in HomoA cells (percentage of reduction compared to cells cultured without ERAP2: 45%; p < 0.03), i.e., cells that naturally produced the full-length form of the protein." (PMID 31379846, 2019). "Initially, we investigated the non-independent impact of two main ERAP2 SNPs rs2549782 and rs2248374 on HIV-1 infection outcome." (PMID 38980912, 2024). "Data herein also indicate that exogenous ERAP2-FL exerts its protective function against HIV-1 infection, even in HomoB subjects who do not genetically produce it." (PMID 31379846, 2019). "The ERAP2 haplotype A may exert effects relevant to HIV-1 infection but not for chronic T cell responses." (PMID 38980912, 2024). "Additional results indicated that the rs2549782-G ERAP2 polymorphism is significantly more represented in an Italian cohort of HESN (HIV exposed seronegative individuals) subjects who, despite repeated exposure to HIV-1 infection, do not seroconvert." (PMID 32183384, 2020).
birdshot chorioretinopathy (5 papers, 2018 to 2024). Birdshot chorioretinopathy is a posterior uveitis characterized by multiple cream-colored, hypopigmented choroidal lesions in the fundus and a strong association with HLA-A29 and clinically presenting with blurred vision, floaters, photopsia, scotoma and nyctalopia. "Both ERAP1 and ERAP2 polymorphisms have an influence on the HLA-A*29-bound immunopeptidome, providing an explanation for their association with birdshot chorioretinopathy." (PMID 35769458, 2022).
COVID-19 (5 papers, 2021 to 2022). A disease caused by infection with severe acute respiratory syndrome coronavirus 2. "For example, ERAP2, a risk factor for COVID-19-associated death, is upregulated in lung squamous cancer and negatively associated with patient prognosis." (PMID 35141230, 2021). "For instance, ERAP2 is a risk factor for COVID-19-related death and it is upregulated in lung squamous cancer but is negatively associated with the patient prognosis." (PMID 35141230, 2021). "In line with this hypothesis, a missense variant in the ERAP2 gene has been linked to an increased risk of death in a small cohort of COVID-19 patients from the U.K. Biobank." (PMID 33567739, 2021). "Under the pandemic of SARS-CoV-2, ERAP2 abnormity is related to the unfavorable clinical outcomes of COVID-19 infected patients, while ERAP2 may also inspire the development of the vaccine." (PMID 34992605, 2021). "Hence, ERAP2-targeted treatment may simultaneously reduce COVID-19 disease severity and restrain cancer progression." (PMID 35141230, 2021). "In this context, given the role of ERAP enzymes in the regulation of RAS, hypertension, antigen processing, inflammatory disorders, and cytokines and NO release, we hypothesize that knowledge of ERAP1 and ERAP2 genotypes may be useful in identifying the appropriate therapy for each COVID-19 patient." (PMID 33567739, 2021). "Therefore, targeting ERAP2 might be a potential treatment target to both relieve COVID-19 severity and restrain cancer progression." (PMID 35141230, 2021). "Some of us, due to bad luck, improper genetic constitution (among it, the presence or absence of ERAP2) and environmental influence, contract serious or even fatal diseases, but our species as a whole survives even the worst pandemics such as cholera, plague, AIDS, or, now, COVID-19." (PMID 35769458, 2022).
Hypertension (5 papers, 2018 to 2024). The presence of chronic increased pressure in the systemic arterial system. "The authors found three SNPs (ERAP1 rs469783 and rs10050860; ERAP2 rs2927615) to be associated with the risk of incident hypertension and one variant (ERAP1 rs27772) associated with blood pressure progression." (PMID 33567739, 2021). "Zee and colleagues evaluated the potential association of 33 ERAP1 and 12 ERAP2 single nucleotide polymorphisms (SNPs) with blood pressure progression and incident hypertension in a cohort of 17,255 initially healthy White U.S. women." (PMID 33567739, 2021). "Multivariable Cox regression analysis showed an association of three tSNPs (ERAP1: rs469783 and rs10050860; ERAP2: rs2927615; all p < 0.05) with risk of incident hypertension." (PMID 29850473, 2018). "Results from the multivariable Cox regression analysis showed evidence for an association of three SNPs (ERAP1: rs469783 and rs10050860; ERAP2: rs2927615; all p-uncorrected <0.05) with risk of incident hypertension." (PMID 29850473, 2018). "(ii) Three ERAP1 and ERAP2 tSNPs are associated with risk of incident hypertension." (PMID 29850473, 2018). "However, to date, no systematic, prospective epidemiological data are available that examine the relevance of the ERAP1 and ERAP2 gene loci as risk markers for hypertension." (PMID 29850473, 2018). "The present study suggests that ERAP1 and ERAP2 gene variation may be useful for risk assessment of BP progression and the development of hypertension." (PMID 29850473, 2018). "ERAP2/Iso3, and also ERAP1 low activity allotypes, cannot perform these functions, thus moving equilibrium to stimulation of AT1R which causes vasoconstriction and hypertension." (PMID 35769458, 2022). "In conclusion, the present findings provide evidence for the involvement of ERAP1 and ERAP2 gene loci in blood pressure regulation and the pathogenesis of hypertension with an added indication of ERAP1 gene locus as a potential therapeutic target for blood pressure management." (PMID 29850473, 2018). "Defective variants of ERAPs (i.e., low activity ERAP1 allotypes and lack of functional ERAP2) exacerbate the impact of SARS-CoV-2 on hypertension and organ damage." (PMID 35769458, 2022).
Behçet’s disease (4 papers, 2019 to 2025). "Polymorphisms in the endoplasmic reticulum aminopeptidase (ERAP) genes, namely ERAP1 and ERAP2, have recently been shown to be much more prevalent in individuals with ankylosing spondylitis (AS), psoriasis, or Behçet’s disease (BD), according to genetic association studies." (PMID 40098955, 2025).
lung carcinoma (4 papers, 2014 to 2022). "ERAP1 was lost in all tested breast, ovary, and lung carcinomas and in 6 out of 7 liver carcinoma samples tested, whereas ERAP2 was retained only in 9 out of 26 samples." (PMID 25566501, 2014). "In conclusion, our study is the first to intensively illustrate the role of ERAP2 in lung cancer." (PMID 34992605, 2021). "Also, in nonsmall cell lung cancer some ERAP1 allotypes were associated with cancer risk, protection, or without effect, depending on the presence versus absence of ERAP2 (ERAP2 separately was without effect)." (PMID 35769458, 2022). "Remarkably, in four types of carcinomas (breast, ovary, liver, and lung carcinomas) arising from normal counterparts co-expressing ERAP1 and ERAP2, none of the 26 tested samples retained this phenotype." (PMID 25566501, 2014).
viral infections (4 papers, 2012 to 2022). "The genetic signals at the ERAP2 locus suggest at least three perfectly linked variants on Haplotype B affecting ERAP2 transcription and splicing in response to viral infection." (PMID 30446528, 2018). "Given the documented role of ERAP2 in antigen presentation and viral infections, we examined the genetic control of ERAP2 transcripts in the human antimicrobial response." (PMID 32847031, 2020). "It was discovered recently that the defective ERAP2 gene, not encoding functional aminopeptidase, may nevertheless, during viral infections, produce a truncated protein isoform of unknown function, possibly interfering with ERAP1 and full-length ERAP2 by heterodimer formation." (PMID 35769458, 2022). "In addition, the defective ERAP2 allele is not without function in immune defense as, in viral infections, it produces truncated protein isoform possibly interfering with ERAP1 and functional (allotype A) ERAP2." (PMID 35769458, 2022).
bladder cancer (3 papers, 2020 to 2023). "Recently, endoplasmic reticulum aminopeptidase 2 (ERAP2) expression has been associated with a better outcome in patients with bladder cancer treated with immunotherapies." (PMID 33810334, 2021). "Patients with the luminal subtype of bladder cancer showed an improved response to anti-PD-L1 immunotherapy in the setting of low ERAP2 expression." (PMID 36834865, 2023). "Expression of ERAP2 (endoplasmic reticulum aminopeptidase 2), a pan-cancer gene associated with MHC-I antigen processing, predicted survival in bladder cancer patients receiving ICI therapy." (PMID 32582553, 2020).
breast carcinoma (3 papers, 2014 to 2022). "This association between EpCAM and ERAP2 suggests a new mechanism of EpCAM processing and regulation of antigen presentation in breast cancer." (PMID 25265904, 2014). "The endoplasmic reticulum aminopeptidase 2 (ERAP2) has been identified by our group as an EpCAM‐associated protein, and here we continue this effort and present another novel finding that Annexin A2 (ANXA2) is a potential interacting partner of EpCAM in the EpCAM+ ERα+ breast cancer cells." (PMID 34240826, 2022).
cervical cancer (3 papers, 2020 to 2023). A primary or metastatic malignant neoplasm involving the cervix. "In the current study, we found an association between rs2287988 in ERAP2, which is responsible for a synonymous polymorphism (Q563Q), and cervical cancer." (PMID 32321463, 2020). "Our results indicated that rs27044, rs26618 and rs26653 in ERAP1 and rs2287988 in ERAP2 influenced susceptibility to cervical cancer." (PMID 32321463, 2020). "ERAP1/ERAP2 polymorphisms have been associated with cervical cancer and autoimmunity." (PMID 37173324, 2023). "The results showed that the ERAP1 haplotype, rs27044C-rs30187T-rs26618T-rs26653G-rs3734016C and the ERAP2 haplotypes, rs2549782T-rs2548538T-rs2248374G-rs2287988A-rs1056893T and rs2549782G-rs2548538A-rs2248374A-rs2287988G-rs1056893T may be associated with cervical cancer risk." (PMID 32321463, 2020). "Moreover, the G allele of rs2287988 in ERAP2 may be associated with a higher risk of cervical cancer (OR = 1.187, 95% CI: 1.057–1.332)." (PMID 32321463, 2020). "Six single nucleotide polymorphisms (SNPs) in ERAP1 and 5 SNPs in ERAP2 were selected and genotyped in 556 CIN patients, 1072 cervical cancer patients, and 1262 healthy control individuals." (PMID 32321463, 2020). "The ERAP2 haplotypes rs2549782G- rs2548538A-rs2248374A-rs2287988G-rs1056893T (P = 0.009 and 0.006) and rs2549782T-rs2548538T-rs2248374G-rs2287988A-rs1056893T (P = 0.003 and 0.009) might be associated with cervical cancer and the development from CIN to cervical cancer." (PMID 32321463, 2020). "In the current study, we evaluated the influence of ERAP gene (ERAP1 and ERAP2) polymorphisms on susceptibility to cervical intraepithelial neoplasia (CIN) and cervical cancer." (PMID 32321463, 2020). "The allelic frequencies of rs27044 in ERAP1 and rs2287988 in ERAP2 were significantly different between control and cervical cancer groups (P = 0.003 and 0.004)." (PMID 32321463, 2020). "In the current study, we found that genetic polymorphisms in ERAP1 and ERAP2 genes might be associated with CIN and cervical cancer, and suggested that polymorphisms in key antigen-processing genes could affect susceptibility of cervical cancer." (PMID 32321463, 2020). "In cervical cancer, ERAP1 and ERAP2 proteins have been reported to be highly variable, ranging from low to high expression levels." (PMID 32321463, 2020). "Additionally, the allelic and genotypic distributions of rs2248374 (P = 0.015 and 0.041, respectively) and rs2287988 (P = 0.014 and 0.039) in ERAP2 were significantly different between CIN and cervical cancer groups." (PMID 32321463, 2020). "There were no SNPs in ERAP1 or ERAP2 that exhibited a significantly different distribution between the CIN and control groups or between the CIN and cervical cancer groups after Bonferroni correction (P > 0.0045)." (PMID 32321463, 2020).
malaria (3 papers, 2010 to 2020). Malaria is a serious and sometimes fatal disease caused by a parasite that commonly infects a certain type of mosquito which feeds on humans. "Even more intriguing is the observation that the ERAP2 variants co-segregating with a lower or null expression of ERAP2 (G at rs75862629 and G at rs2248374, respectively) appear more frequent in the equatorial regions, where the malaria has been endemic." (PMID 32793222, 2020). "It is therefore conceivable that malaria is the factor that has favored the establishment of polymorphisms correlating with a lower expression of ERAP2." (PMID 30740100, 2019). "In conclusion, functional variants of the three aminopeptidases ERAP1, ERAP2, and LNPEP show a worldwide distribution compatible with a selective pressure by malaria." (PMID 30740100, 2019). "Is this because a lower expression of ERAP2 confers some protection from the most severe form of malaria?" (PMID 30740100, 2019). "Interestingly, a lower activity of ERAP2 has been correlated with a basal diastolic higher pressure, whose implication as a protective factor against malaria is becoming an increasingly accredited hypothesis." (PMID 30740100, 2019). "There is no known link between malaria and ERAP2 genotypes, and the signatures of selection are observed in non-malaria-suffering regions." (PMID 20976248, 2010).
oral cavity squamous cell carcinoma (3 papers, 2017 to 2022). A squamous cell carcinoma arising from the oral cavity. "Recent studies report that ERAP2 is an oncogenic gene, overexpressed in variant cancers, such as glioblastoma, choriocarcinoma and oral cavity squamous cell carcinoma (OSCC)." (PMID 36214762, 2022). "ERAP2 overexpression in patients with oral cavity squamous cell carcinoma has been associated with metastasis from the primary tumor and poor prognosis, while the absence of ERAP2 in choriocarcinoma cells reduced their ability to activate T lymphocytes." (PMID 33406696, 2021).
Yersinia pestis infection (3 papers, 2022 to 2025). "They demonstrated the effect of the rs2549794 variant of the ERAP2 gene on macrophage function and response to Yersinia pestis infection." (PMID 37964883, 2023).
atopic dermatitis (2 papers, 2022 to 2023). "Genetic polymorphisms in ERAP2 have been previously associated with atopic dermatitis risk, suggesting a potential role in the development of atopy." (PMID 37175432, 2023).
choriocarcinoma (2 papers, 2021 to 2022). An aggressive malignant tumor arising from trophoblastic cells. "For example, the absence of ERAP2 in choriocarcinoma has been linked to the reduction of the activation of T lymphocytes by the tumor cells." (PMID 33810334, 2021).
colon carcinoma (2 papers, 2018 to 2022). "To verify whether this co-localization was a special feature of the MDMs or if the presence of the “short” ERAP2 was a sufficient condition, we took advantage of two colon carcinoma cell lines, Caco-2 and LoVo." (PMID 35563348, 2022). "Interestingly, DG013A, a first generation pseudopeptide containing a phosphinic group was a potent inhibitor of ERAP1 and ERAP2 activity and was demonstrated to enhance CD8+ T-cell responses against a murine colon carcinoma cell line." (PMID 30054427, 2018).
diabetes (2 papers, 2011 to 2020). "Inter-racial differences in the prevalence of comorbidities, such as obesity and diabetes, may partly explain these observations, but ethnic variants of single-nucleotide polymorphisms have also been identified, such as in the endoplasmic reticulum aminopeptidase 2 (ERAP2) gene." (PMID 32679789, 2020).
Hodgkins lymphoma (2 papers, 2021 to 2025). A heterogeneous group of malignant lymphoid neoplasms of B-cell origin characterized histologically by the presence of Hodgkin and Reed-Sternberg (HRS) cells in the vast majority of cases. "Immunohistochemistry was done on 10 cHL (5 nodular sclerosis and 5 mixed cellularity) cases with membranous HLA class I expression in Hodgkin Reed-Sternberg cells and with homozygosity of the minor (n = 5) or major (n = 5) allele of the ERAP2 NMD SNP." (PMID 33499248, 2021).
leukemia (2 papers, 2021 to 2023). A malignant (clonal) hematologic disorder, involving hematopoietic stem cells and characterized by the presence of primitive or atypical myeloid or lymphoid cells in the bone marrow and the blood. "The ERAP2 SNP rs2549782 showed a strong eQTL effect on ERAP2 expression in the cell line panel including 40 lymphoma and leukemia cell lines." (PMID 33499248, 2021).